GAPDH (glyceraldehyde-3-phosphate dehydrogenase)
Diseases named in the same sentence as GAPDH in open-access papers (continued):
Sharing a sentence is not in itself a finding about the gene and the disease.
breast carcinoma (continued). "GAPDH was used as an internal reference protein in breast cancer cells." (PMID 35726220, 2022). "We examined the levels of AR protein in the three different TNBC cell lines (BT549, MDA-MB-453, and SUM159PT) and compared these to AR protein in the ER+/AR+ MCF7 breast cancer cell line by 1D western blots normalizing the AR band intensity to that of GAPDH as a loading control." (PMID 36584207, 2022). "In our study of MCF-7 breast cancer cell line, we identified GAPDH-CCSER2-PCBP1 triplet as the most stable reference gene triplet which could be used to normalize the expression of genes of interest in various nutrient stress conditions." (PMID 34681026, 2021). "Similarly, GAPDH gene expression correlates with breast cancer grade, overall survival, and disease-free survival." (PMID 34073074, 2021). "However, GAPDH and TBP in hepatic cancer cell lines and ACTB and B2M in breast cancer cell lines have M values > 1, which causes us to consider them as unstable reference genes." (PMID 34752497, 2021). "Changes in GAPDH abundance is related to the development and aggressiveness of breast cancer." (PMID 34571787, 2021). "A relationship between GAPDH with breast cancer has been described; therefore, it could be interesting to further analyze the relevance of the GAPDH-derived peptides presented by these cells." (PMID 34868006, 2021). "Moreover, similar to the geNorm output, TBP, and GAPDH for hepatic cancer cell lines and B2M for breast cancer cell lines were sorted as the least stable reference genes." (PMID 34752497, 2021). "Additionally, AMPK-triggered nuclear translocation of GAPDH leads to Sirt-1 release from the complex deleted in breast cancer-1 (DBC-1), an inhibitor of Sirt-1, thereby enhancing Sirt-1 transcriptional activity." (PMID 33049944, 2020). "Additionally, GSTP1 was recently shown to modulate glycolytic metabolism in breast cancer cells by enhancing glyceraldehyde-3-phosphate dehydrogenase (GAPDH) activity." (PMID 32526885, 2020). "To determine whether the GAPDH active site Cys is sensitive to IR outside of E. coli, we performed identical irradiation treatment using the human breast carcinoma cell line MDA-MB-231 (abbreviated 231)." (PMID 32536603, 2020). "The effect is most likely caused by an up‐regulation of GAPDH expression (and glycolysis) in breast cancer tissue that leads to fast interaction of Pi with GAPDH, which is also seen in muscle tissue and brain tissue, with high GAPDH expression and similar short T2 values for Pi." (PMID 30311703, 2019). "Definite proof for the proposed T2 shortening of Pi due to up‐regulated GAPDH expression (and glycolysis) could be obtained from comparing multi‐echo 31P MR spectra of knock down GAPDH breast cancer xenografts with non‐modified breast cancer xenografts." (PMID 30311703, 2019). "However, the increase in GAPDH expression due to ageing is only minor as compared with the increased GAPDH expression as a consequence of breast cancer, where an average increase of a factor of 4 has been reported." (PMID 30311703, 2019). "Among the differentially expressed proteins, the 60 kDa heat shock protein, the adenylate kinase A4 as well as the glyceraldehyde-3-phosphate dehydrogenase and the Fructose-bisphosphate aldolase A, were significantly up regulated in the hereditary breast cancer cells compared to the sporadic model." (PMID 29584711, 2018). "However, some single genes were also used to measure DNA levels – particularly GAPDH in a series of 4 publications on breast cancer, and hTERT in 4 publications." (PMID 29061138, 2017). "Furthermore, GAPDH expression is upregulated via activation of the hypoxia-inducible factor (HIF-1) in breast cancer cells." (PMID 26350063, 2015). "Based on reports of increased glyceraldehyde-3-phosphate dehydrogenase, pyruvate kinase, and lactate dehydrogenase in breast carcinomas, we hypothesized that glycolytic metabolism genes would be increased in primary breast cancer specimens." (PMID 26316122, 2015).
breast carcinoma (continued). "For GAPDH, similar findings were noted in basal breast cancer cells." (PMID 25617865, 2015). "Moreover, YWHAZ, UBC, and GAPDH showed the highest stability in breast cancer cell lines." (PMID 34752497, 2021). "Therefore, whether GAPDH can be used rightfully as a reference protein requires further investigations in breast cancers." (PMID 33194682, 2020). "Thus, GAPDH mRNA expression in breast cancer seems to reflect tumor aggressiveness." (PMID 24252137, 2013). "The expression of Claudin-5 was examined in breast cancer specimens (tumour, n = 106; background, n = 27) using real-time quantitative Polymerase Chain Reaction (all values are displayed as mean Claudin-5 transcript copies/μL of cDNA from 50 ng total RNA and normalised by GAPDH)." (PMID 22559840, 2012). "SNHG5 has also been shown to enhance glycolytic flux in breast cancer through the miR-299/BACH1 axis, promoting the expression of glycolytic enzymes such as HK2, PFK1, and GAPDH." (PMID 41550840, 2026). "We isolated TDEs from E0771 breast cancer cell supernatant and validated their identity by CD9, CD63, and GAPDH expression, nanoparticle tracking analysis (NTA), and transmission electron microscopy (TEM)." (PMID 40695812, 2025). "Disrupted expression of core circadian genes (BMAL1, CLOCK and PER3) and hub genes such as ACTB, GAPDH and CDK1 suggests that circadian gene dysregulation promotes breast cancer progression and represents a potential therapeutic target." (PMID 41908013, 2025). "As a proof of principle, using only plasmid HDR template, we also tagged two proteins, GAPDH and FASN, in a breast cancer cell line MDA-MB468 with a FLAG tag." (PMID 37487103, 2023). "As examples, we tagged GAPDH and FASN in the breast cancer cell line MDA-MB468, although no further analysis was performed at this stage." (PMID 37487103, 2023). "In this work, it isdescribed an electrochemical genosensor forthe detection of glyceraldehyde-3-phosphate dehydrogenase (GAPDH)gene transcripts, which we found to be overexpressed in breast cancercells and exosome-derived human serum in breast cancer patients." (PMID 36683335, 2023). "GAPDH, a commonly used reference gene, and UBC were the most stable in EV derived from liver and breast cancer cell lines." (PMID 37510317, 2023). "During cancer development and progression, glycolysis and glyceraldehyde-3-phosphate dehydrogenase (GAPDH) played an important role, such as in colorectal adenocarcinoma and breast cancer." (PMID 35547257, 2022). "Another eight ARGs (BCL2, BIRC5, EIF4EBP1, ERO1L, FOS, GAPDH, ITPR1, and VEGFA) were explored, and the author found that these genes not only were significantly associated with overall survival but also could predict distant metastasis-free survival in breast cancer." (PMID 34869345, 2021). "In the breast cancer tissue group DNAJC8, RPL13A, and TARDBP were the most stably expressed genes, while ACTB, B2M, and GAPDH were the least stably expressed genes." (PMID 34895237, 2021). "It was concluded that GSTP1 interacts with glyceraldehyde-3-phosphate dehydrogenase (GAPDH) and increases its enzyme activity in breast cancer cells." (PMID 33946704, 2021). "In previous breast cancer studies, commonly used RGs included beta-actin (ACTB), glyceraldehyde-3-phosphate dehydrogenase (GAPDH), beta-glucuronidase (GUSB), ribosomal protein L13a (RPL13A), and tubulin alpha 1a (TUBA1A)." (PMID 34895237, 2021). "Our results overally indicated that GAPDH, YWHAZ, and UBC were the most stable reference genes in breast cancer cell lines, including MCF7, SKBR3 and MDA-MB231, and B2M and ACTB were the least stable ones." (PMID 34752497, 2021).
breast carcinoma (continued). "In the breast cancer tissue group, TRA2B, RHOA, and THRAP3 were the most stable genes, and DNAJC8, GAPDH, and B2M were the most unstable genes." (PMID 34895237, 2021). "In the breast cancer tissue group, the three most stably expressed genes (with the lowest M values) were SF1, THRAP3, and TARDBP, while GAPDH, DNAJC8, and B2M were the least stably expressed genes." (PMID 34895237, 2021). "Recently, on the basis of the GEO database, Gu and his colleagues constructed an ARG model consisting of eight genes (BCL2, BIRC5, EIF4EBP1, ERO1L, FOS, GAPDH, ITPR1, and VEGFA), which can be used as an independent prognostic indicator of breast cancer." (PMID 32649310, 2020). "We applied projection electrophoresis to immunoblotting analyses of well-characterized endogenous proteins GAPDH and actinin across populations of individual human BT474 breast cancer cells." (PMID 33277486, 2020). "The results showed that PARP1, GAPDH, and FOS protein were less expressed in normal breast tissues but were moderately expressed in breast cancer tissues." (PMID 32649310, 2020). "Further, under acidic pHi conditions, provoked by hypoxia and MCT1/2 inhibition, the additional knockdown of GAPDH, and to a lesser extent of GPI, triggered cell death, especially in more aggressive AA MCF7 breast cancer cells." (PMID 30065243, 2018). "BT20, HCC1806 and MDA-MB-468 human breast cancer cells were treated with DAC and/or TSA and CREB3L1 mRNA levels were analyzed by qPCR, relative to a GAPDH-specific control." (PMID 26810754, 2016). "Core metabolic prognostic signatures are identified, comprising NUDT1 and GAPDH in kidney renal cell carcinoma and SQLE, ALG3 and PSPH in two independent breast carcinoma cohorts." (PMID 27358048, 2016). "Using GAPDH as a reference, western blotting revealed that the expression of CA1 was significantly increased in the breast cancer samples, compared to the breast fibroadenoma samples (p = 0.008)." (PMID 26459317, 2015). "For normalization of cells without transfection treatments, 18S rRNA and ACTB would be appropriate across all cells, and GAPDH and ACTB would be appropriate in basal breast cancer cells." (PMID 25617865, 2015). "As mammalian miRNAs regulate target genes predominantly by acting to decrease target mRNA levels, we first compared the mRNA levels of those genes between breast cancer sample and its NAT by real-time PCR with GAPDH used as an internal control." (PMID 25394902, 2014). "GAPDH and ACTB were among the least and the most stable genes which a in concordance with other breast cancer studies." (PMID 21702980, 2011). "Among various breast cancer subtypes, including luminal (n = 8), HER2 (n = 2), TNBC (n = 8), and TAMR (n = 4), the relative expression of lncRNA IGF2-AS/GAPDH was significantly higher in TAMR breast cancer patients compared to patients with other subtypes (p < 0.01)." (PMID 41007650, 2025). "Therefore, given that GAPDH expression is upregulated by HIF-1α, future studies are required to investigate the relevance of the HIF-1α/GAPDH axis to breast cancer cell survival in terms of radioresistance, chemoresistance, and angiogenesis." (PMID 40214422, 2025). "UM-UC5 and UM-UC9 bladder cancer cells and BT-20 and MDA-231 breast cancer cells were treated with 10 uM ambrosin over a 48 h time course before cellular proteins were isolated for Western blotting and probed with anti-PARP and anti-GAPDH antibodies." (PMID 40754248, 2025). "Our results suggest that DC-5163 is a promising GAPDH inhibitor for suppressing breast cancer growth without obvious side effects." (PMID 38811918, 2024). "In addition, GUSB, TUBA1A, RPL13A, and B2M, which previous studies suggested being stable RGs in breast cancer research, and two classical RGs, ACTB and GAPDH, were also considered." (PMID 34895237, 2021). "In contrast, breast cancer tissues of overweight/obese women showed higher PFK-1 and GAPDH protein expression compared to breast cancer tissues of normal-weight women." (PMID 34073074, 2021).
breast carcinoma (continued). "Breast cancer tissue in normal-weight women shows more pronounced glycogen deposition, while breast cancer tissue in overweight/obese shows higher protein expression of PFK-1 and GAPDH glycolytic enzymes." (PMID 34073074, 2021). "GAPDH is very promising target for the treatment of a wide range of tumors, in contrast to other specific anticancer agents, such as Herceptin, which is used in the treatment of HER2-positive breast cancer only." (PMID 31612140, 2019). "Other top key drivers like VEGFA, GAPDH and PPARG also play a role in breast cancer and obesity." (PMID 29156709, 2017). "After normalizing to the GAPDH mRNA levels, the expression level of the FLNa mRNA was 0.634±0.53 in the breast cancer tissues and 0.06±0.01 in the distant non-tumor breast tissues (P<0.05)." (PMID 24137390, 2013). "On the basis of our findings, we suggest that TFRC is the most stable EC, ACTB and TFRC is the best combination of two reference genes to quantify uPA, and that using RPLP0 and GAPDH are not recommendable for breast cancer." (PMID 21702980, 2011). "RNA from a variety of breast cancer cell lines along with non-neoplastic cell lines was blotted and GAPDH expression was monitored as an internal control to normalize expression." (PMID 18721486, 2008). "We compared its expression at mRNA levels by RT quantitative real-time PCR relative to GAPDH in ERα”—positive (n = 54) and ERα”—negative (n = 45) breast cancer tissues to their matched normal tissues." (PMID 21655374, 2008). "We establish here a cut of value of 5 × 106 copies per 1010 mRNA copies of GAPDH with an Odds Radio of 39.4, Sensitivity of 0.81 and Specificity of 0.90 in breast cancer tissues that are negative for ERα protein by IHC and estrogen binding assays." (PMID 17391528, 2007). "We chose to use 28S rRNA as a comparative control because glyceraldehyde-3-phosphate dehydrogenase is not recommended in breast cancer." (PMID 16280049, 2005). "Therefore, to confirm the roles of these genes on the vital regulatory mechanisms in breast cancer, we compared the potential role of novel RGs (SF1, TRA2B, THRAP3, RHOA, and QRICH1) vs. traditional RGs (ACTB, and GAPDH) in the normalization of target gene expression." (PMID 34895237, 2021). "Hence, many studies suggest not to use GAPDH as a control gene to study breast cancer or they rank GAPDH as the least stable gene." (PMID 32977762, 2020). "Therefore, GAPDH has not been suggested to be a control RNA to study breast cancer." (PMID 25617865, 2015). "In comparison, breast cancer tissue showed no prominent glycogen deposition but displayed higher PFK-1 and GAPDH protein expression in overweight/obese women." (PMID 34073074, 2021). "The mRNA expression of all candidates, in comparision with GAPDH, was analyzed in basal type (MDA-MB-231) and hormone positive (HR(+)), HER2 negative (HER2 (−)) type MCF7 breast cancer cell lines." (PMID 25136922, 2014). "Regular abundance of HuR to GAPDH mRNA, ie without RNA-IP, was 0.3 in HEK293 cells (data not shown) and 0.5–1.0 in the breast cancer cells." (PMID 23401122, 2013). "Depletion of RPL24 in breast cancer cells by >70% reduced cell viability by 80% and decreased protein expression of the eIF4E-dependently translated proteins cyclin D1 (75%), survivin (46%) and NBS1 (30%) without altering GAPDH or beta-tubulin levels." (PMID 24970821, 2014). "Importantly, mRNA levels of the tumor suppressor gene claudin-6 (CLDN6) reported to be increased in breast cancer cells upon DAC treatment were induced in all cell types regardless of their subtype classification, while GAPDH mRNA, a house keeping gene did not change following DAC treatment." (PMID 25860442, 2015).
lung carcinoma (76 papers, 2006 to 2025). "Previous studies have reported that the expression IGF2BP1, TLR8, PIWIL4, and GAPDH were associated with tumorigenesis and progression of lung cancer patients, which consistent with our results." (PMID 32087603, 2020). "A study performed in human lung carcinoma indicates that the NAD+ binding domain of GAPDH is associated with telomere and that telomere binding activity of nuclear GAPDH is regulated by sphingolipid ceramide in a cell cycle dependent manner." (PMID 31027346, 2019). "Increased GAPDH expression is associated with the proliferation and invasion of lung cancer." (PMID 39165641, 2024). "For instance, existing research demonstrates that GAPDH exhibits apoptotic and antiproliferative potential against lung cancer cells in both in vitro and in vivo models." (PMID 40129771, 2025). "To validate the influence of GAPDH on the GLO system we reduced GAPDH activity in vitro in the following manner: I) through siRNA-mediated knockdown of GAPDH; or II) pharmacological inhibition using koningic acid (KA) in A549 and H358 lung cancer cells." (PMID 40461450, 2025). "BACH1 suppresses mitochondrial activity by reprogramming the glucose utilization into glycolytic metabolism via upregulating the transcription of glycolytic genes, including HK2 and GAPDH, in lung cancer cells." (PMID 40263598, 2025). "In this regard, we identified glyceraldehyde-3-phosphate dehydrogenase (GAPDH) as the main regulator of the glyoxalase system in lung cancer cells." (PMID 40461450, 2025). "Our combined comprehensive ex vivo redox analysis suggests that lung cancer at the same time reinforces oxidative metabolism while reducing MG production by increased GAPDH activity." (PMID 40461450, 2025). "For lung cancer datasets, namely LUAD_CPTAC and LUSC_CPTAC, both GAPDH RNA and protein levels show significant positive correlations with most m6A regulatory proteins (p < 0.05)." (PMID 38928396, 2024). "The top candidate exosomal proteins associated with lung cancer, based on the number of publications supporting the association, included SPP1, CD44, ALB, SPARC, CAT, GAPDH, and CADM1." (PMID 39766023, 2024). "Heat shock proteins (HSP), especially HSP70 and GAPDH which are conserved across species, were used to stain proteins in basil EV and mammalian EVs (A431 lung cancer cell)." (PMID 38939903, 2024). "The bioinformatics-based association analysis identified candidate exosomal proteins associated with lung cancer, including SPP1, CD44, ALB, SPARC, CAT, GAPDH, and CADM1." (PMID 39766023, 2024). "BACH1 is able to activate the transcription of Hexokinase 2 and GAPDH and thereby promotes lung cancer metastasis." (PMID 38818308, 2024). "GAPDH participates in telomere maintenance in the nucleus of human lung carcinoma cells; under stresses, the translocation of glyceraldehyde-3-phosphate dehydrogenase from cytoplasm to the nucleus is regulated by acetylation." (PMID 36651565, 2023). "Raw cycle threshold (CT) values were first normalized to the GAPDH expression of each lung cancer cell line before comparing expression to Beas2B." (PMID 35136486, 2022). "More importantly, a significant role of GAPDH in the progression of colon cancer, liver cancer and lung cancer has been established." (PMID 36559193, 2022). "It has been found that the high expression of GAPDH is related to the proliferation and invasion of lung cancer and esophageal cancer." (PMID 35190747, 2022). "Glyceraldehyde-3-phosphate dehydrogenase (GAPDH) is a glycolytic enzyme and one of the main housekeeping proteins, and its increased expression is correlated with the proliferation and invasion of lung cancer." (PMID 34323652, 2021). "To further determine the expression of these hub RBPs in LUAD, we used immunohistochemistry results from the Human Protein Atlas database to show that IGF2BP1, PABPC1, and GAPDH were significantly increased in lung cancer compared with normal lung tissue." (PMID 32087603, 2020).